IL10 (interleukin 10)
Diseases named in the same sentence as IL10 in open-access papers (continued):
Sharing a sentence is not in itself a finding about the gene and the disease.
Hepatitis (70 papers, 2007 to 2026). Inflammation of the liver. "A previous study has highlighted the critical role of IL-10 in preventing hepatitis caused by the migration of intestinal T cells to the liver in mice infected with T. spiralis." (PMID 39421828, 2024). "The liver protective effect was abolished in IL-10-deficient mice and administration of recombinant IL-10 rescued these mice from chemical-induced hepatitis." (PMID 27770815, 2016). "Another study showed that increased numbers of circulating IL-10+ Bregs and CD4+CXCR5+Foxp3+ follicular regulatory T (TFR) cells are associated with poor virus eradication and liver injury in CHB patients and that serum IL-10 levels are associated with hepatitis flare." (PMID 35163476, 2022). "At day 9 p.i., a decrease of chlamydial antigen was observed in all groups except IL-10-tg mice, where a multifocal hepatitis and chlamydial antigen was observed." (PMID 39199857, 2024). "P. goldsteinii promotes the production of Treg cells and IL-10 and improves prediabetes syndromes and liver inflammation." (PMID 37737162, 2023). "IFN-γ blockade has been shown to be effective in the repeated TLR-9 model, while monomethyl fumarate, which upregulates IL-10 production via HO-1, ameliorates cytopenia and hepatitis." (PMID 36964620, 2023). "Studies have shown that IL-10 played an anti-fibrosis role in the Progression of liver inflammation and also played an important regulatory role on TNF-α." (PMID 36615846, 2022). "The results of previous studies suggest that IL-10 ameliorates the symptoms of ConA-induced hepatitis." (PMID 33919375, 2021). "Of note, also the HBvac NR who was the only individual without protective anti-HBs titer even after booster with third-generation hepatitis B vaccine had very low frequencies of IL-10 expressing CD24+CD27+ and CD24highCD38high Breg and B10+ cells." (PMID 34566969, 2021). "A significant increase in the number of DCs in infected mouse livers, with higher CD86 expression and IL-4, IL-10 and IL-12 secretion, suggested that DCs were involved in S. japonicum infection-induced hepatitis." (PMID 34692568, 2021). "Selection of these biomarkers was made based on the literature data suggesting that TNF-α, IFN-γ, IL-6, and IL-10 are important mediators in the development of ConA-induced hepatitis, and activities of transaminases are reliable indicators of liver damage." (PMID 33919375, 2021). "Currently, the administration of IL-10 is considered as a tentative pharmacological tool in the treatment of liver inflammation and fibrosis." (PMID 34926704, 2021). "This suggestion is in accordance with an analysis of TLR2 responsiveness in PBMCs of a small cohort of HBeAg-positive CHB patients, indicating that TNF and IL6 are induced in the hepatitis phase, whereas IL10 dominates the response in immune tolerant patients." (PMID 32632817, 2021). "The results showed that the level of IL-10 was significantly increased by unmodified ERCs, and was further upregulated by Gal-9 high-expressing ERCs, leading to much reduced severity of hepatitis." (PMID 34654474, 2021). "IL-10 has been reported to be triggered by LPS, and elevated serum IL-10 was positively correlated with degree of liver inflammation." (PMID 35126359, 2021). "As the severity of liver failure increases, the level of IL-10 in serum of patients with hepatitis increases, and the decrease in methylation of IL-10 promoter plays an important role in IL-10 gene activation." (PMID 32582189, 2020). "Hepatitis patients with increased liver failure will lead to IL-10 promoter methylation and IL-10 gene inactivation." (PMID 32582189, 2020). "ConA-induced hepatitis in mice is prevented by exogenous IL-10 and exacerbated by anti-IL-10 mAb or IL-10 KO." (PMID 30177931, 2018). "Accordingly, to find the therapeutic target of treating hepatitis, the molecular mechanism of IL-35 affecting KCs-derived IL-10 needs to be studied in the future." (PMID 30197594, 2018).
Hepatitis (continued). "It has been reported that IL-10 is crucial for tolerance induction in hepatitis and is mainly expressed by Tregs and Kupffer cells." (PMID 25478691, 2014). "Elevated IL-10 levels in males suggested that this cytokine directly or indirectly suppresses pro-inflammatory responses that induce hepatitis." (PMID 23577207, 2013). "IL-10 is an anti-inflammatory cytokine: LPS-induced hepatitis is more evident in IL-10-knokout mice than in wild-type mice." (PMID 22536224, 2012). "In our cohort of patients with CHB it was difficult to distinguish the influence of viraemia or liver inflammation, since both were increased in patients with elevated levels of IL-10." (PMID 21187913, 2010). "At day 28 p.i., neither antigen nor inflammation was observed in WT-V mice; some chlamydial antigen and hepatitis could be observed in the other groups of mice, with a higher level in IL-10-tg-c mice particularly." (PMID 39199857, 2024). "The current study revealed significant increased levels of both cytokines IL-6 and IL-10 among those who were good responders to the hepatitis B vaccine boosters, with a significant positive correlation between these cytokines (IL-6 and IL-10) and anti-HBsAb titre." (PMID 38827254, 2024). "Moreover, a study of patients with CHB experiencing a spontaneous flare showed a close temporal correlation between IL-10 levels and fluctuations in viral load or liver inflammation." (PMID 35163476, 2022). "High levels of immunomodulatory lymphocytes and related cytokines such as regulatory B cells (Breg) and IL-10 have been associated with serological non-response to hepatitis B vaccination." (PMID 34566969, 2021). "Moreover, CH4 enhanced GSK-3β activation, thus leading to an increased expression of the anti-inflammatory cytokine IL-10, similar to the findings for a carbon tetrachloride–derived liver inflammation model." (PMID 31807906, 2019). "Similar to its functions in IBD, IL-10 also exerts protective functions during liver inflammation." (PMID 31244763, 2019). "Our observations about the importance of IL-10 are in harmony with a prior work, which revealed the essential role of IL-10 in preventing the migration of intestinal T cells to the liver and inhibiting the development of hepatitis in mice infected with T. spirals." (PMID 28761478, 2017). "Moreover, increasing expression of IL-10 in the serum was found in response to chronic active hepatitis B, which is positively correlated with liver inflammation." (PMID 24976843, 2014). "This anti-IL-10 result suggested to us that anti-IL-10 did not have a direct effect on sex differences seen in our model and suggested to us an indirect effect of IL-10 that may help to explain worsening hepatitis in female mice." (PMID 23577207, 2013). "In the study of peripheral blood mononuclear cells (PBMCs) collected from acute Q fever patients, the production of TNF, IL-6, IL-12, and IL-10 was higher than in control subjects, and TNF and IL-10 levels were higher in patients with hepatitis than in those with isolated fever." (PMID 20594295, 2010). "In addition, berberine decreased the production of TNF‐α, IFN‐γ, IL‐2, IL‐1β, increased the level of IL‐10 and alleviated hepatitis by blocking the transcriptional activity of signal transducer and activator of transcription 1 (STAT1), which was largely dependent on activating AMPK." (PMID 35263512, 2022). "Additionally, a recent study has also reported that the administration of DSS changed the expression of pro-and anti-inflammatory cytokines such as IL-1β, IL-10, and TGFb-2, suggesting that intestinal inflammation led to liver inflammation, thus, these results supported our finding again." (PMID 34603071, 2021). "With reference to liver cytokine milieu, IL-10 levels showed an inverse relation with fibrosis severity (significant fibrosis p = 0.0398, advanced fibrosis p = 0.0291) whereas TNF-α and TGF-β were associated with hepatitis severity (p = 0.0409, p = 0.0321; respectively)." (PMID 29038590, 2017).
Hepatitis (continued). "Since cytokines in the serum had been reported to be associated with liver inflammation and dysfunction, patients with liver dysfunction had significantly higher level of IL-2R, IL-6, IL-10, and TNF-α in the serum, when compared with those without liver dysfunction (p < 0.001)." (PMID 29109622, 2017). "Aithal reported that the frequencies of the variant alleles for IL-10 and IL-4 were significant higher in patients with diclofenac-induced hepatitis compared with both healthy controls and subjects on diclofenac without hepatitis." (PMID 25789467, 2015). "By contrast, LPS-treated hepatitis mice administered 1-MNA exhibited significantly higher nitrogen oxide levels compared to both the LPS and IL-10 knockdown groups." (PMID 40018042, 2025). "It is likely, that innate immune signaling by TLR2 is involved in the hepatitis phase of CHB and is controlled by IL10 in the infection phase." (PMID 32632817, 2021). "IFN-α has been successfully used for the treatment of hepatitis and we wondered if IFN-α has any effects on IL-17 and IL-10." (PMID 24484458, 2014). "Although the cells and cytokines that mediate liver damage in IL-10−/− mice have yet to be clearly identified, it has been established that overproduction of IFN-γ and TNF-α can promote the development of severe hepatitis during acute MCMV infection." (PMID 22880122, 2012). "Additionally, both pro-inflammatory and anti-inflammatory genes, such as Cd163, Ho-1, Il-1β, Il-10, and Ccl5, along with CD163 and HO-1 protein expression, were markedly suppressed, supporting the notion of alleviated liver inflammation." (PMID 41522337, 2026). "By primarily activating the anti-inflammatory cytokine (IL-10) mediated JAK1/STAT3 signaling pathway, PAE also effectively reduced oxidative stress-induced liver inflammation while also reducing liver damage, as evidenced by the reductions in serum AST and ALT." (PMID 36139880, 2022). "In post-hepatitis HCC patients, a higher frequency of peripheral IL-10+ CD19+CD24+hiCD38+hi Bregs was found compared to patients with chronic HCV (Hepatitis C Virus), HCV-related liver cirrhosis, or healthy controls and was positively correlated with CD4+FoxP3+ Tregs and serum IL-10, IL-35 levels." (PMID 36618354, 2022). "The levels of several other inflammatory mediators, i.e., IL-1β, IL-4, IL-10, IL-12, and IL-17A, were measured in the serum of mice with ConA-induced hepatitis in the presence and absence of GRMS-55." (PMID 33919375, 2021). "Cytokines with immunmodulatory function such as IL-10 and TGF-β are involved in induction of tolerance in Con-A-mediated hepatitis and may as well play a role in our model." (PMID 26599014, 2015). "We found that hepatitis as measured by inflammation score was not different between groups (0.7±0.1 (anti-IL-10) versus 0.8±0.5 (isotype), n = 4 BALB/c males/group, mean ± S.E.)." (PMID 23577207, 2013). "Furthermore, the pro-inflammatory effect of the IL-10/IL-17A ratio was observed in patients with advanced MASLD in comparison with those without liver inflammation." (PMID 40918132, 2025). "In addition, in one mouse model of MASLD, SB reduced hepatitis activity according to the NAS scale, production in the liver of TNF-α, IL-1β, interferon-γ, and IL-10 as well as the inflammatory cell chemoattractant CCL-2 and macrophage (Kupffer cells) biomarker F4/80." (PMID 39203520, 2024). "The time courses of four inflammatory mediators, namely IFN-γ, IL-6, IL-10, and TNF-α and the activities of both transaminases, i.e., ALT and AST, in the mice serum were modeled using the newly designed PK/PD/disease progression model of GRMS-55 in ConA-induced hepatitis in mice." (PMID 33919375, 2021). "Moreover, STAT3 could also be activated by several other factors including IL-22, IL-10, ECG and hepatitis viral proteins, suggesting that further well designed studies should be conducted to explore the association between them and the risk of ATDH." (PMID 25789467, 2015).
Hepatitis (continued). "However, male mice that received anti-IL-10 blocking antibodies did not exhibit enhanced hepatitis compared to mice that received isotype controls." (PMID 23577207, 2013). "The median concentration of IL-10 in plasma showed a clear decreasing trend from healthy controls to NASH, as well as from hepatitis without significant fibrosis to liver cirrhosis." (PMID 37569857, 2023).
uveitis (69 papers, 2009 to 2025). An inflammatory process affecting a part of or the entire uvea. "Tests involving the detection of cytokines like interleukin 6, interleukin 10, and PCR detection of pathogenic nucleic acids hold significant clinical relevance in uveitis diagnosis." (PMID 40851860, 2025). "Results showed, using q-PCR, that the mRNA levels of IFN-γ, IL-17, IL-4, and IL-10 in the liver tissues of the rats in the EAU group were significantly associated with the progression of uveitis." (PMID 40718791, 2025). "In a previous study, intravitreal (IVT) adeno-associated virus (AAV) harboring equine interleukin-10 (eqIL-10) cDNA inhibited experimental uveitis in rats." (PMID 39703903, 2024). "Here, we describe the use of an AAV vector encoding a codon optimized Equine-IL10 cDNA, a natural cytokine that is known to play a major role in inducing ocular immune privilege, for the treatment of uveitis using AAV gene therapy." (PMID 35980983, 2022). "Our data suggest that the aetiology-specific inflammatory mediators that are elevated in the disease entities associated with uveitis included in this study are IL-10 in IOL, RANTES and IFN-α2 in ARN, and IL-6, IL-17A, IL-22, and G-CSF in BE." (PMID 32066796, 2020). "In addition to IL-10 +434T and +504G minor alleles, the patients with uveitis and chronic uveitis had significantly more frequently IL-10 -2849TT genotype than Finnish control population." (PMID 30779760, 2019). "Our results suggest that IL-10 polymorphisms may have a role in susceptibility to TIN/TINU while genetic variation in TNF-α gene may be connected to isolated uveitis." (PMID 30779760, 2019). "Elevated intraocular IL-10 levels were previously associated with activity of uveitis and it was hypothesized that elevated levels of IL-10 represent an attempt to control the inflammation." (PMID 21850175, 2011). "Besides, clinical uveitis can be caused not only by IL-1 but also by other cytokines such as IL-6, IL-10, and tissue necrosis factor, etc." (PMID 19693263, 2009). "Research has demonstrated that the ratios of pro-inflammatory cytokines to IL-10 in aqueous humor differed significantly among patients with various clinical types of uveitis." (PMID 40433375, 2025). "LXD effectively improved patients' vision and reduced uveitis recurrence in prior trials by modulating IL-10 and IL-17 expression in anterior uveitis treatment." (PMID 40918405, 2025). "The roles of IL-10 and IL-6 have been extensively explored in various ocular diseases, including uveitis, where cytokine analysis has been widely proposed for differential diagnosis." (PMID 40433375, 2025). "IL-10, in particular, has been studied extensively in uveitis and has shown potential as a therapeutic agent in reducing ocular inflammation." (PMID 40433375, 2025). "IL-10 plays an important role in uveitis by protecting the eye from chronic inflammation and helping to prevent relapses of inflammation." (PMID 39703903, 2024). "Recently, our laboratories demonstrated that AAV-equine IL-10 (AAV-eqIL-10) effectively inhibits uveitis in the well-established experimental autoimmune uveitis (EAU) rat model of NIU." (PMID 39703903, 2024). "Samples from mouse eyes injected subretinally with AAV-IL-10 had IL-10 concentrations of 204–406 pg/mL (mean 308 pg/mL), sufficient to inhibit the development of experimental uveitis." (PMID 39703903, 2024). "Here, we found that the levels of CSF IL-10 were also elevated in 22 out of the 23 vitreoretinal B-cell lymphoma patients, while the CSF IL-10 levels were within normal limits in the control uveitis group." (PMID 36059608, 2022). "Intravitreal Equine-IL10 provides a long-term ocular anti-inflammatory therapeutic that would be an effective, novel therapeutic strategy for refractory and recurrent uveitis as well as other ocular autoimmune inflammatory diseases." (PMID 35980983, 2022). "Studies have shown that levels of the cytokines IL-6 and IL-10 are elevated in the aqueous humor of patients with uveitis." (PMID 36761168, 2022).